Y_RNA (Y RNA )
Gene: Miscellaneous RNA gene on chromosome 15 (44,843,612 to 44,843,724, forward strand). Ensembl gene ENSG00000238845.
Homologues: Orthologues: macaque Y_RNA (91% identical). Paralogues in human: RNY1 (88% identical), Y_RNA (88% identical), Y_RNA (87% identical), Y_RNA (86% identical), Y_RNA (85% identical), RNY1P11 (84% identical), RNY1P7 (84% identical), Y_RNA (84% identical), RNY1P8 (83% identical), Y_RNA (83% identical), Y_RNA (82% identical), Y_RNA (81% identical), and 97 more.